WNT3A (Wnt family member 3A)
Diseases named in the same sentence as WNT3A in open-access papers (continued):
Sharing a sentence is not in itself a finding about the gene and the disease.
cancer (continued). "To address this, we compared the ability of the extract to inhibit the Wnt pathway when activated by Wnt3a vs. LiCl at 15 mM (a concentration within the standard range for induction of the Wnt signaling in cultured cancer cells)." (PMID 28931883, 2017). "In this study, we show that cancer cells can secrete canonical Wnt signaling ligands (Wnt3a) to activate AMSCs to a TAF-like phenotype." (PMID 26060426, 2015). "There was a significant downregulation of mRNA levels of mortalin and several other proteins, including MMPs, vimentin, β-catenin, TGF-β and Wnt-3a, involved in cancer cell metastasis in embelin-treated cells as compared to their control counterparts." (PMID 26376435, 2015). "Overall, our understanding of Wnt3a is incomplete, and molecular mechanisms of its specific roles remain to be further studied in various diseases, including cancer." (PMID 26369691, 2015). "In this study, we assume that an activation of Wnt signaling is an effect of AMSCs response to Wnt signaling hyperactivated cancer cell lines that aberrantly expressing Wnt ligands, such as the Wnt3a, an essential component in the Wnt signaling pathway." (PMID 26060426, 2015). "Adding Wnt3a into cancer cell lines with low E-cadherin expression significantly increased TOPflash reporter activity; this was consistent with previous data showing that nuclear β-catenin expression is responsive to Wnt stimulation." (PMID 26075748, 2015). "We first tested the effects of RBM47 on cancer cell Wnt responsiveness by treating WT6 cells with recombinant Wnt3A and subsequently measuring the expression of AXIN2, a common TCF/β-catenin target gene and a general marker of Wnt activity." (PMID 24898756, 2014). "Anchorage-independent growth, one of the most important malignant features of cancer cell stemness, was found to be significantly increased in cells overexpressing Wnt3a." (PMID 25499541, 2014). "WNT3A treatment caused a significant increase in MS in the MCF7 and MDA-MB-231 cancer cell lines while MCF10a immortalised normal breast cells were less sensitive." (PMID 23861811, 2013). "In human cancer, Wnt3a appears to function both as oncogene and tumor suppressor gene in different cancer cell lines." (PMID 23815780, 2013). "We also investigated the potential function of the candidate Wnt-inhibitor miR-1 in the Wnt-dependent HT29 cancer cell line, because miR-1 was identified as one of the strongest repressors of Wnt-3a-induced activation of the STF reporter." (PMID 22043311, 2011). "We found that SOX4 interacts with plakoglobin in a WNT3A-dependent manner in our experimental cancer model." (PMID 22098624, 2011). "The synergy that we observed between Activin and Wnt3a has previously been reported in normal mouse development and in the context of human cancers." (PMID 20502661, 2010). "We show that ectopically expressed Wnt3a pulls down FZC18 in vitro and that FZC18 suppresses Wnt3a-dependent activation of Wnt signaling in human cancer and embryonic kidney cells." (PMID 18382662, 2008). "We think that these oncogenic features may confer a growth advantage to KRAS-mutant cancer cells under 3D culture conditions, especially in our system, where additional growth factors such as Wnt3a, R-spondin-1, and Noggin were excluded." (PMID 40462147, 2025). "Notably, we avoided using organoid culture media components such as Wnt3a, R-Spondin-1, and Noggin, which are known to influence the molecular subtypes of cancer cells." (PMID 40462147, 2025). "For example, in cancer, Wnt3a has been shown to activate both Wnt/Ca++ and Wnt/β-catenin." (PMID 38586172, 2024). "However, in HUH7 cells, Wnt3a treatment reduced the cancer effect (54 lipids represented in green bars) rather than promoting it (22 lipids represented in red bars)." (PMID 37699867, 2023).
cancer (continued). "Previous studies have shown that through activation of the Wnt/β-catenin signaling pathway, Wnt3a can promote the epithelial-mesenchymal transition (EMT) process and enhance the metastatic properties of cancer cells, both of which are closely associated with the formation of VM." (PMID 37407689, 2023). "What’s more, HOXB3 knockdown in LNCaP-AI and hCAF (human cancer-associated fibroblasts) cells didn’t change WNT3A expression (data not shown)." (PMID 36973255, 2023). "Taken together, TOP2A and Wnt3a may play an important role in VM formation and cancer progression in NSCLC." (PMID 37407689, 2023). "Moreover, WNT3A, a well-known prototypical Wnt ligand, is also known to play an important role in cancer metastasis through the Wnt signaling pathway by regulating extracellular matrix adhesion and invasion." (PMID 36555553, 2022). "GC-derived EVs induced PMCs infiltration by activating Wnt3a/β -catenin signaling, infiltrating PMCs, and in turn, promoting the subserosal invasion of cancer cells, and mutual attraction between cancer cells and PMCs accelerated tumor invasion which ultimately led to peritoneal metastasis." (PMID 35173726, 2022). "The effectors such as PI3K and Wnt3a participate in different activities of cancer cells." (PMID 33663486, 2021). "In cancer, the loss of WNT16 may facilitate excessive canonical WNT activation by failure to compete with more potent WNT ligands, such as WNT3A and WNT8." (PMID 32384699, 2020). "However, Wnt3a has recently been considered as an oncogenic factor in cancers of colon, breast, lung, and esophageal squamous cell." (PMID 31737122, 2019). "Wnt3a protein was dimly expressed in all the corresponding adjacent non-carcinoma samples." (PMID 31528227, 2019). "Therefore, we harvested cells with Wnt3A-conditioned media and investigated the change in β-catenin signaling in cancer cells treated with RSPO2." (PMID 29383135, 2017). "Wnt3a was upregulated in 64.8% cancer tissues compared to normal tissues." (PMID 28358374, 2017). "In addition, our results showed that upregulation of miR-491-5p inhibited the expression of Wnt3a in MKN45/SGC-7901 cancer cells." (PMID 28358374, 2017). "Consistent with this new role for AurkA in controlling the stem-like subpopulation through Wnt3a/β-catenin signaling, a direct consequence seems that AurkA may affect chemoresistance and recurrence in cancer patients." (PMID 27341528, 2016). "Herein, we summarize the latest findings on Wnt3a as an important therapeutic target in cancer." (PMID 26369691, 2015). "In addition, western blotting demonstrated that nuclear β-catenin was significantly increased only in cancer cell lines that expressed low levels of E-cadherin after stimulation with Wnt3a as compared with cells treated with control medium." (PMID 26075748, 2015). "Wnt3a can either suppress or promote cancer cell growth, depending upon cancer types." (PMID 26369691, 2015). "Additionally, proteins that are overexpressed in cancer cells are among the targets of down-regulated miRNAs in different treatment conditions, which includes Wnt3A, PPARα, UCP2, CSF1, and MED1." (PMID 24387052, 2014). "In the present study, we analyzed wnt3a and wnt5a to determine their roles in cancer progression." (PMID 24564183, 2014). "Thus, we show that the distribution of β-catenin complexes in APC-mutant cancer cells is highly similar to those of Wnt3a-stimulated cells." (PMID 25392450, 2014). "Taken together, these data show that TQ could be touted as complementary phyto-compound with tumoricidal activity to alter the protein levels of intracellular effectors such as PI3K and Wnt3a which are important in multiple cancer cells bioactivities such as metastasis and vasculogenic mimicry." (PMID 33663486, 2021).
cancer (continued). "Validation of these data exhibited that chemokines involved in promoting macrophage polarization and cancer metastasis, including CCL11 and CCL26, were stimulated by Wnt3a signaling and their expression was abrogated by treatment with rSFRP1." (PMID 38554160, 2024). "We then analysed the expression of WNT ligands (WNT7B, WNT9A, WNT3A, WNT4) in RBL2-LOH cancer cell lines (HCC1500 and Cal-51) and in RBL2-wildtype cancers (MCF7 and T47D)." (PMID 38678032, 2024). "Nevertheless, we decided to focus on WNT3A because of its high dysregulation in HNC, in addition to its correlation with cancer metastasis, which coincided with our functional results." (PMID 36555553, 2022). "In particular, RANKL overexpression in PC3 cells led to a significant increase in expression of Wnt3a, suggesting that RANKL is a potential target of Wnt signalling in cancer cells." (PMID 34108600, 2021). "miR-766-3p is also known as a dual player in cancer, it showed an anti-cancer effect on HCC by targeting WNT3A, but it is also known to inhibit cell-cycle progression and metastasis of RCC by targeting SF2 and HCC by targeting MTA3, respectively." (PMID 33435549, 2021). "In conclusion, our results indicate that GOLPH3 enhances the secretion of exosomes containing CKAP4 and WNT3A, which activate the WNT/β-catenin pathway, thereby contributing to metastasis and the cancer stem cell-like phenotype in NSCLC." (PMID 34671013, 2021). "Among these target genes, KLK9, WNT3A, FGF18, FIBP, SOX12, TGFBI, and NEDD9 have been reported to participate in the development of human cancers." (PMID 33344223, 2020). "Significantly elevated Wnt3a expression levels were detected in squamous cell lines EPC-1 and EPC-2, while metaplastic (CP-A), dysplastic (CP-B) and carcinoma cell lines (OE33, OE19) showed only marginal expression of Wnt3a." (PMID 30841855, 2019). "It has been reported that miR-195 suppresses the proliferation, migration, invasion and radiosensitivity of cancer cells through directly targeting some oncogenes, including CARM1, YAP, GDPD5 and WNT3A." (PMID 30487160, 2018). "miRNA-491 has been evaluated mostly in cancer, but it has been shown that target mRNAs involved in strong profibrotic pathways including TGF-β/SMAD3/NF-κB and Wnt3a/β-catenin signaling pathways." (PMID 30530916, 2018). "Platelets are activated by the interaction with cancer cells and release several soluble mediators (such as PGE2, TXA2, PDGF, TGF-β and Wnt3a) and MPs/exosomes." (PMID 26551717, 2015). "In the present study, Wnt3a and mimicking of Wnt signaling through LiCl and BIO resulted in induction of both PLD1 and PLD2 in a variety of cancer cells." (PMID 20711340, 2010). "Although cells with WT and functional BRCA1/BRCA2 activate the canonical Wnt/β-catenin–dependent signaling pathway upon Wnt3A treatment, cancer cells that lose BRCA1 function activate the noncanonical β-catenin–independent pathway instead." (PMID 39028933, 2024). "Additionally, LINC01405 upregulation led to the increased cell populations, proliferation, and upregulation of critical cancer‐related genes, including AKT1, AKT3, mTOR, WNT3A, SMAD3, CYCLIN D1, CYCLIN D2, BCL2, and GSK3B." (PMID 38225865, 2024). "In SNU475 cells, we observed that Wnt3a treatment amplifies the cancer effect (42 lipids represented in red bars) rather than moderating it (33 lipids represented in green bars)." (PMID 37699867, 2023). "The LPS-positive group showed significantly greater cancer stromal TGFBI expression (p < 0.0001), more HER2-negative cases (p = 0.012), greater PD-L1 expression (p = 0.0029), increased wnt3a signaling (p = 0.0028) and lower E-cadherin expression (p = 0.0055) (EMT marker) than the LPS-positive group." (PMID 37511547, 2023). "The immunohistochemical staining technique was employed to assess the expression of Wnt3a and β-catenin in both cancer and adjacent noncancerous tissues." (PMID 37859826, 2023).
cancer (continued). "Moreover, cryptolepine downregulated WNT3a-induced expression of MMP2 and MMP9 genes, which are involved in cancer cell invasion." (PMID 37513937, 2023). "Growth factors for cancer organoid culture include Wnt3A, R-spondin-1, TGF-β receptor inhibitor, epidermal growth factor, and Noggin, but the combination and concentration of these factors added to the media depend on the specific cancer type." (PMID 36713421, 2022). "Furthermore, AGO2 related RIP assays showed that circ0101675, miR-1278 and WNT3A/5A were all enriched to AGO2 RNA binding protein in both H1299 and A549 cancer cells." (PMID 34093821, 2021). "For example, Wnt3a accelerates the autophagic level in neurons by modulating the GSK‐3β‐AMPK axis, but not the Wnt/β‐catenin pathway, indicating that a β‐catenin‐dependent or independent signal can generate cancer cells with a radioresistant phenotype." (PMID 31111621, 2019). "Therefore, the expression pattern of the Wnt3a protein in 222 primary LSCC, and 19 corresponding adjacent non-carcinoma specimens, was detected by immunohistochemistry and further correlated with clinicopathological parameters." (PMID 31528227, 2019). "Moreover, some of markers were related to cancer progression, like IGF2, PTGS2, WNT3A, according to our literature review." (PMID 28415743, 2017). "Therefore, to check for correlation if any, between DKK4, β–catenin, Wnt3a and c-Myc expression in HCC, we searched the ONCOMINE human cancer genomics database." (PMID 27272409, 2016). "Since Wnt3a/β-Catenin pathway is one of the major signaling pathways involved cancer cell migration and invasion, we studied whether 4-HPR was able to interfere with the Wnt3a pathway in MB cells." (PMID 27367907, 2016). "Importantly, the replication stress–induced chromosomal breaks in these CIN+ cancer cells were also efficiently suppressed upon Wnt10b, but not Wnt3a treatment." (PMID 40846632, 2025). "Moreover, Wnt3a was overexpressed in CRC primary tissues than in metastatic areas, suggesting that Wnt3a was expressed early in cancer rather than appearing as it progressed." (PMID 39200196, 2024). "Therefore, we believe that cancer invasion may be one of the main functions of miR-503 in HNC and is inhibited through the regulation of WNT3A." (PMID 36555553, 2022). "However, the interaction between Wnt3a and miR-497-5p in malignant tumors has not been reported yet." (PMID 35419295, 2022). "In a model of cancer pain (osteolytic fibrosarcoma cells in the calcaneus bone), we found that non-neuronal cells release Wnt3a, which triggers DRG neurons via non-canonical pathways enhancing the membrane translocation of P2X purinoceptor 3 (P2X3) and TRPV1 receptors." (PMID 36231105, 2022). "Moreover, the expression of Wnt3a was higher in the primary sites than that in the metastatic sites of CRC tissues, suggesting that the expression of Wnt3a was induced in the initial period of CRC rather than emerging as the cancer progressed." (PMID 32923386, 2020). "To elucidate whether PKM2 loss in cancer cells is linked to the increase of CSC-like function, we next isolated EpCAM+Lgr5+ cells from polyps and cultured single Lgr5+ CSC without Wnt3a and R-spondin." (PMID 30996297, 2019). "Fifteen members of cancer pathways, including FOS, TGFα, FZD8, MMP1, laminin subunit gamma 2, PTGS2, laminin subunit beta 3, ITGA2, laminin subunit alpha 3, VEGFC, WNT2B, heat shock protein 90 beta family member 1, WNT5B, FGF5 and WNT3A, were up-regulated in the MC group." (PMID 30482199, 2018). "These secreted regulatory proteins may lead to activation of both canonical (Wnt3a) and non-canonical (Wnt5a) Wnt signaling pathways in cancer." (PMID 27323822, 2016). "Although in vitro models (cancer cells/adipocytes) confirmed that phenotype of CAAs may be triggered directly by cancer cells, and some candidate molecules released by tumor cells such as TNF-α, Wnt3a, Wnt5a, and MMP11 have been proposed, the exact mechanism remains elusive." (PMID 33916703, 2021).
cancer (continued). "Unlike single-cancer studies, we uncovered FZD2’s context-dependent functions in both canonical Wnt activation (e.g., Wnt3A/ROR2 axis) and immune evasion mechanisms (e.g., M2 macrophage recruitment)." (PMID 40444048, 2025). "The data show that, when cancer cells were treated with Wnt3a, ATF4 did not further enhance the activity of canonical Wnt signaling, which suggests that ATF4 regulates Wnt/β-catenin signaling mainly through modulating β-catenin stability, similar to Wnt3a." (PMID 33628101, 2021).
infection (24 papers, 2010 to 2025). The state of being infected such as from the introduction of a foreign agent such as serum, vaccine, antigenic substance or organism. "Signaling by Wnt3A and Wnt11 in macrophages and macrophage associated cells of the gut has also been linked with inhibition of infections by pathogenic Pseudomonas and Salmonella species." (PMID 31736969, 2019). "Treatment with 25 mg/kg–50 mg/kg of baicalin raised the protein levels of GSK-3β and β-catenin and inhibited the protein levels of WNT3A and c-Myc compared to the infection group (p < 0.05)." (PMID 40427615, 2025). "Silencing of Wnt3a reduced Delta Vpp infection to 50% and 55%, and Omicron Vpp infection to 53% and 71%." (PMID 38203386, 2023). "Intending to discover druggable host factors, we performed an shRNA screen in human lung adenocarcinoma H1650 and human embryonic kidney 293T (HEK293T) cells and identified Wnt3a as one of the candidates involved in SARS-CoV-2 Spike-mediated infection." (PMID 38203386, 2023). "qRT-PCR and Western blot analysis demonstrated significant reductions in Wnt3a gene expression, which correspondingly diminished Spike Vpp infection to 53% and 47%, indicating that the reduction in Wnt3a expression decreases virus entry." (PMID 38203386, 2023). "After transfection, the cells were infected with HSV-1 or treated for 4 h with Wnt3a-CM prior to infection for 24 h." (PMID 34749529, 2021). "Note that a high number of NSCs with nuclear β-catenin were observed after infection with canonical Wnt AAV (Wnt3a), indicative of active canonical Wnt signaling." (PMID 29296000, 2018). "To determine if Wnt signaling positively regulates RVFV infection, we treated HeLa cells and A549 cells with increasing concentrations of Wnt3A prior to infection." (PMID 27226375, 2016). "The reporter activity remained elevated after 6 and 7 h of treatment with Wnt3A or infection with RVFV MP12-GFP, whereas β-catenin reporter activity peaked at 5 hpi and decreased thereafter in cells infected with RVFV MP12." (PMID 27226375, 2016). "At 48 hr after infection, the cells were stimulated with the canonical ligand Wnt-3A or lithium chloride (LiCl) for an additional 12 hr and then analyzed for luciferase expression." (PMID 23071438, 2012). "Quantitative cell cycle analysis from three batches of experiments showed ectopic expression of core, Wnt3A or core plus Wnt3A significantly promoted G1- to S-phase transition in Huh7 cells, especially at 72 hr and 120 hr post-infection." (PMID 22110662, 2011). "A main finding of our study is that Wnt3a is downregulated by direct infection." (PMID 41156605, 2025). "The 25 to 100 mg/kg of baicalin could enhance GSK-3β and β-catenin mRNA expressions and attenuate WNT3A and c-Myc mNRA expression levels compared to the infection group (p < 0.01)." (PMID 40427615, 2025). "Next, we incubated the cells with Wnt3a-CM prior to infection." (PMID 38203386, 2023). "Furthermore, our study demonstrates that Wnt3a is involved in the infection of not only wild-type SARS-CoV-2, but also Delta and Omicron variants." (PMID 38203386, 2023). "We pretreated the cells with Wnt3a-CM prior to infection to prevent the degradation of β-catenin." (PMID 34749529, 2021). "Contradictory to our data herein, these researchers also observed a concurrent reduction in WNT3A transcript abundance and postulated that L. intracellularis may downregulate β-catenin/Wnt signaling at the peak of infection." (PMID 34147126, 2021). "Wnt3A promotes an anti-inflammatory effect in murine macrophages during infection in lungs." (PMID 31736969, 2019). "Quantitative real-time RT-PCR (qRT-PCR) analysis was used to measure the mRNA expression levels of β-catenin, cyclin D1, Dvl, LRP5, or matrix metalloproteinase-7 (MMP7) after infection with RVFV MP12 or RVFV MP12-GFP (MOI of 1) or treatment with Wnt3A in A549 cells." (PMID 27226375, 2016).